CTLA4 (cytotoxic T-lymphocyte associated protein 4)
Diseases named in the same sentence as CTLA4 in open-access papers (continued):
Sharing a sentence is not in itself a finding about the gene and the disease.
melanoma (continued). "Ipilimumab, a cytotoxic T-lymphocyte-associated protein-4 (CTLA-4) monoclonal antibody, was the first ICI to receive FDA approval in 2011 for treating advanced melanoma." (PMID 40130115, 2025). "Our findings reveal significantly different risk profiles for immune-related neurologic complications in melanoma patients treated with PD-1 inhibitor monotherapy versus those treated with both PD-1 and CTLA-4 inhibitors." (PMID 40351833, 2025). "ICIs—such as programmed death-1 (PD-1), programmed death-ligand 1 (PD-L1), and cytotoxic T-lymphocyte-associated protein 4 (CTLA-4)—have shown remarkable efficacy in treating malignancies, including hepatocellular carcinoma (HCC) and melanoma." (PMID 40361336, 2025). "For example, there was a higher frequency of vitiligo in patients with melanoma in anti-PD-1 therapy and anti-CTLA-4 therapy." (PMID 39866435, 2025). "Incidence of CNS irAEs like meningitis and encephalitis is significantly higher in melanoma patients with history of anti-PD-1/CTLA-4 combination therapy than in those treated with anti-PD-1 monotherapy." (PMID 40351833, 2025). "Butyrate exhibits compartment-specific reversal: mucosal levels (10–100 mM) enhance CD8+ T cell cytotoxicity, but systemic concentrations >2.5 μM in melanoma patients correlate with CTLA-4 blockade resistance and 30% shorter PFS." (PMID 41181090, 2025). "Dual staining with Melanoma Triple Cocktail enabled confirmation of PD‐L1, PD‐1 and CTLA‐4 expression by neoplastic melanocytic cells." (PMID 39789732, 2025). "previously proposed that RIG‐I activation was critical for responsiveness to checkpoint blockade, their results—primarily derived from melanoma B16 cell lines—showed that RIG‐I activation enhanced the therapeutic effects of anti‐CTLA4 therapy." (PMID 40116486, 2025). "Tumor neoantigens more accurately predict outcomes in melanoma patients treated with first-line anti-PD-1 or anti-CTLA-4 therapy compared to other biomarkers such as PD-L1 levels and mutational burden." (PMID 40356925, 2025). "Fecal microbiota transplantation (FMT) from humans to mice demonstrated that anti-CTLA-4 antibody treatment in melanoma patients promotes the expansion of Bacteroides fragilis, which possesses potent anticancer properties." (PMID 40806182, 2025). "Melanoma treatment using ICIs such as nivolumab and pembrolizumab (anti-PD-1) and ipilimumab (anti-CTLA-4 ) is very effective." (PMID 40872475, 2025). "This study included 104 serum samples from 39 patients with resectable stage IIIB-C nodal melanoma receiving neoadjuvant anti-CTLA-4 (ipilimumab) and anti-PD-1 (nivolumab)." (PMID 41291768, 2025). "Inhibition of CTLA-4 has been utilized to promote anti-tumour immunity: ipilimumab, a fully human monoclonal antibody (IgG1) that inhibits CTLA-4, is widely used in the treatment of malignant melanoma and prostate cancer." (PMID 39992258, 2025). "A study found that the average OS of radiotherapy plus ICIs was significantly longer than that of radiotherapy plus CTLA-4 in patients with malignant melanoma and BMs, which was 27.4 and 7.5 months, respectively." (PMID 40917780, 2025). "Ipilimumab, as a CTLA-4 inhibitor, was the first drug proven to prolong OS in patients with advanced melanoma." (PMID 39910672, 2025). "While ICIs such as those targeting CTLA4 have shown success in melanoma, their application in NMSCs remains an emerging area of research." (PMID 40005446, 2025). "Human DC2/moDC and TAM signatures were generated based on our scRNAseq and correlated with three Treg-associated genes (i.e., FOXP3, CTLA4, and TIGIT) in patients undergoing RT of radioresistant tumors (i.e., melanoma, glioblastoma, and head and neck cancer)." (PMID 40146036, 2025). "In a study of patients with melanoma, researchers collected melanoma biopsy samples from patients who underwent CTLA-4 blockade." (PMID 40038799, 2025). "Metastatic melanoma can be treated with anti-PD-1 monotherapy or in combination with anti-CTLA-4 or anti-Lag3." (PMID 40148586, 2025).
melanoma (continued). "Ipilimumab, a fully human IgG1 anti-CTLA-4 antibody, was first approved for use in 2011, initially as a novel therapy for Stage 4 malignant melanoma." (PMID 40265076, 2025). "The RELATIVITY-047 trial demonstrated that combining relatlimab with nivolumab improved PFS over PD-1 monotherapy in unresectable melanoma, with better tolerability compared to CTLA-4-based combinations." (PMID 40647451, 2025). "In conclusion, we report the efficacy of a combined intraperitoneal anti-PD-L1 and anti-CTLA-4 immunotherapy in a F16-B10 murine melanoma model by DWI MRI and ex vivo fluorescence immunohistochemistry." (PMID 40517176, 2025). "While disruption of the IFN signaling pathway in melanoma negatively affects tumor response to anti-CTLA-4 therapy, extensive IFN-γ exposure of melanoma cells increased their resistance to radiotherapy and anti-CTLA-4 treatment." (PMID 41369373, 2025). "In our own human studies, we identified sCTLA-4 to be raised in a melanoma patient cohort and was immunosuppressive, comparable to artificial CTLA4-Ig." (PMID 40265076, 2025). "Prior-ICI antibiotic use is consistently associated with worse survival among melanoma patients receiving ICI, with the greatest detriment seen under combination PD-1 + CTLA-4 regimens." (PMID 40507352, 2025). "Tex markers were associated with immunosuppressive markers and responses to ICB therapies, such as anti-PD1 and anti-CTLA4, particularly in melanoma, kidney, and lung cancers." (PMID 40076932, 2025). "To validate this observation, we selected the representative cohort of melanoma patients treated with anti-PD-1, anti-PD-L1 plus anti-CTLA-4 treatment (PRJEB23709)." (PMID 41020834, 2025). "Example immune regulatory protein targets of interest in the field of melanoma include programmed cell death protein 1 (PD‐1), programmed death ligand‐1 (PD‐L1), cytotoxic T‐cell lymphocyte antigen‐4 (CTLA‐4), and lymphocyte‐activation gene 3 (LAG‐3)." (PMID 40457714, 2025). "In terms of treatment, the advent of immune checkpoint inhibitors, such as anti-PD-1 (nivolumab and pembrolizumab) and anti-CTLA-4 (ipilimumab) antibodies, has revolutionized the management of advanced melanoma." (PMID 40191195, 2025). "In the early 2000s, Ipilimumab, the first CTLA-4 inhibitor, entered clinical trials and demonstrated remarkable efficacy in patients with melanoma." (PMID 40012016, 2025). "In that study, patients with anti-PD-1 ICI-refractory melanoma were randomized to anti-CTLA-4 ipilimumab monotherapy or the ipilimumab and nivolumab doublet in the second line." (PMID 40082438, 2025). "PD‐1/PD‐L1 and CTLA‐4 are clinically important immune checkpoints in human melanoma, as the introduction of ICI treatment has significantly improved the outcome for patients with advanced disease." (PMID 39789732, 2025). "For these features melanoma has high potential to elicit specific anti-cancer responses to immunotherapy targeting immune checkpoints, such as PD-1 and CTLA-4." (PMID 40317004, 2025). "Given the toxicity profile of anti-CTLA-4 and the duration of therapy investigated, adjuvant therapy with either anti-PD-1 agents or dabrafenib–trametinib for patients with BRAF-mutated melanoma is preferred." (PMID 39550033, 2025). "Inhibitors targeting CTLA-4, such as ipilimumab, have shown success in the cancer immunotherapy field, particularly for skin cancer (melanoma)." (PMID 40870970, 2025). "In melanoma studies, the central TI induced by nanobiators can enhance the efficacy of PD-1/CTLA-4 inhibitors - ultimately building a bridge between innate immunity and adaptive immune responses." (PMID 41403926, 2025). "In a large multicentre study involving 361 melanoma patients treated with ipilimumab across six hospitals in Switzerland and the Netherlands, the relationship between 10 CTLA-4 SNPs and treatment outcomes was explored." (PMID 41244914, 2025).
melanoma (continued). "This was confirmed when mice administered fecal microbiota transplantation of B. fragilis from melanoma patients overcame CTLA-4 blockade resistance." (PMID 40927726, 2025). "In 3 separate cohorts of patients with melanoma who were treated with anti-PD-L1 or anti-CTLA4 therapy, low ZNF638 was significantly predictive of response." (PMID 40091830, 2025). "This approach opens avenues for melanoma patients who express antigens beyond the most well-known ones like PD-L1 or CTLA-4." (PMID 39857682, 2025). "A study demonstrated that increased expression of PD-L1, post-azacitidine treatment, elevated the anti-PD1 therapy response, while in melanoma, lower CTLA-4 methylation resulted in a better response to anti-CTLA-4 or PD1 therapy." (PMID 40011240, 2025). "The efficacy of ICIs in melanoma was first highlighted with the approval of ipilimumab, an anti-CTLA4 antibody which marked a milestone in cancer immunotherapy." (PMID 40406130, 2025). "Ipilimumab is a CTLA4 neutralizing antibody approved as a monotherapy for advanced melanoma, whereas a second CTLA4 antagonist, Tremelimumab, is approved for combination use with other checkpoint inhibitors in cases of liver cancer." (PMID 39404738, 2025). "A combination of anti-CTLA-4 and anti-PD-1 treatment is highly efficacious for treating melanoma and is being tested in several clinical trials for various cancers." (PMID 40313772, 2025). "In fact, Portuguese patients with BRAF wild-type melanoma were unable to access the combination therapy (in the 1L or subsequently), limiting their treatment options to use anti-PD-1 and anti-CTLA-4 treatments separately." (PMID 40027067, 2025). "Baseline circulating CD8+ Tem frequencies correlate with better OS and clinical response in patients with advanced melanoma receiving anti-CTLA-4, as well as in other cancer patients treated with PD1/PD-L1 axis inhibitor." (PMID 40299510, 2025). "Intriguingly, in melanoma cells, GALNT7 silencing was associated with increased IL-10 secretion, enhanced CTLA-4 expression, and the modulation of immune evasion." (PMID 40824763, 2025). "Melanoma cells often exploit immune checkpoints such as PD-1/PD-L1 and CTLA-4, which serve as crucial modulators of T cells activity." (PMID 39857682, 2025). "Combining vaccines with ICIs, such as anti-PD-1/PD-L1(Programmed death-ligand 1) and anti-CTLA-4, can counteract immune evasion and boost T cell responses in melanoma patients." (PMID 40746887, 2025). "PD-1 checkpoint inhibitors such as nivolumab and pembrolizumab, alone or in conjunction with anti-CTLA-4 agents, demonstrated significant efficacy in enhancing the body’s immune response against melanoma cells." (PMID 40647451, 2025). "According to our results, the early vascular CEUS parameter WiAUC indicates to serve as functional perfusion biomarker of early therapy response under combined anti-PD-L1/anti-CTLA-4 immunotherapy in melanoma." (PMID 40591551, 2025). "Expression of viral mimicry genes correlated with immunotherapy response and DNMT inhibitor treatment enhanced the response to anti-CTLA-4 therapy in a mouse model of melanoma." (PMID 40307913, 2025). "Ipilimumab was the first CTLA-4 inhibitor approved by the FDA in 2011 for the treatment of melanoma." (PMID 41226056, 2025). "Among the 100 melanoma patients treated with CTLA-4 ICI therapy (ipilimumab), having more than one irAE was associated with better cancer outcomes." (PMID 40563660, 2025). "The checkpoint inhibitor pathways like CTLA-4 and PD-1/PD-L1/PD-L2 are important in both MF and melanoma, but have been more extensively studied in melanoma due to their earlier utilization in IMT." (PMID 40843796, 2025). "Here, we describe the case of a patient with advanced melanoma treated with combined anti-CTLA-4 and anti-PD-1 therapy who developed severe left hip pain during treatment." (PMID 41229492, 2025).
melanoma (continued). "Numerous tumor cell lines, including those from the breast, colon, lung, ovarian, uterine, bladder, osteo/rabdomyosarcoma, neuroblastoma, and melanoma, express CTLA-4." (PMID 39905036, 2025). "In a melanoma mouse model, daily oral administration of Lactobacillus reuteri alongside PD-L1 and CTLA-4 inhibitors significantly improved antitumor activity and survival." (PMID 41472726, 2025). "Melanomas from patients who developed brain metastases contained significantly higher levels of (CD45+) immune cells and overexpressed fibronectin and CTLA-4 in all ROIs compared to the melanomas that had metastasized to other sites than the brain (p<0.05)." (PMID 40621453, 2025). "The use of immune checkpoint inhibitors like PD-1, PD-L1, and CTLA-4 has enhanced the survival outcomes for certain cancer patients, particularly those with malignant melanoma, gastric carcinoma, and hepatocellular carcinoma." (PMID 41142608, 2025). "In particular, immune checkpoint blockade, which targets inhibitory receptors such as CTLA-4 and PD-1/PD-L1, has shown significant clinical benefit in specific cancer types such as melanoma and non-small cell lung cancer." (PMID 40108668, 2025). "In 2011, the U.S. Food and Drug Administration (FDA) approved the CTLA-4 inhibitor ipilimumab for the treatment of advanced melanoma, marking the first significant clinical breakthrough for immune checkpoint inhibitors." (PMID 40260303, 2025). "In one study, a negative correlation was observed between CRABP2 and immune checkpoint molecules PD-1, PD-L1, and CTLA-4 across various types of tumors, including breast cancer, melanoma, gastric cancer, and testicular germ cell tumors." (PMID 39991584, 2025). "Immune checkpoint therapy that targets cytotoxic T-lymphocyte-associated protein 4 (CTLA-4) and programmed cell death protein 1 (PD-1) significantly increased the survival of melanoma patients." (PMID 40870970, 2025). "This approval further demonstrates the value of CTLA-4 blockade beyond melanoma and underscores the therapeutic value of dual checkpoint inhibition." (PMID 40561796, 2025). "Immune checkpoint inhibitors (ICIs) blocking cytotoxic T-lymphocyte associated protein 4 (CTLA-4) and programmed cell death protein 1 (PD-1) have shown promising clinical efficacy in patients diagnosed with melanoma." (PMID 40574005, 2025). "We tested the Fc-optimized ipilimumab in combination with anti-PD-1 antibodies in this aggressive melanoma model, mimicking one of the main indications of anti-CTLA-4 antibodies in patients with cancer." (PMID 40460830, 2025). "Similar results examining an increase in a progenitor exhausted PD1+ TCF1+ CD8+ population were reported by Miller and co-authors (2019) in patients with melanoma receiving anti CTLA-4 combined with anti-PD1 therapy." (PMID 40299510, 2025). "In melanoma mouse models, the combined application of anti-CTLA-4 monoclonal antibody (ipilimumab) and IL-15 significantly enhances NK cell activation and improves their cytotoxic effects against B lineage acute lymphoblastic leukemia cell lines (Nalm-6)." (PMID 40463500, 2025). "The search strategy employed combinations of the following keywords and MeSH terms: (“immune checkpoint inhibitors” OR “anti-PD-1” OR “anti-PD-L1” OR “anti-CTLA-4”) AND (“melanoma”) AND (“artificial intelligence” OR “machine learning” OR “deep learning”)." (PMID 40305346, 2025). "In this study, using a murine model of melanoma, cognitive function tests, and neuroimmunological assays, we investigate the cellular mechanisms and impact of combinatorial blockade of CTLA-4 and PD-1 on brain function." (PMID 40313772, 2025). "The highest 5-year OS rate among therapies for advanced melanoma was observed with combined anti-CTLA-4 and anti-PD-1 checkpoint inhibition, which is most strongly associated with the highest incidence of immune-related adverse events." (PMID 41369373, 2025).
melanoma (continued). "In the context of tumor immunology, previous reports have shown upregulation of the inhibitory receptors PD-1 and CTLA-4 in CD4+ TILs cultured with Matrigel-inlaid melanoma organoids." (PMID 40837221, 2025). "PD‐1 and CTLA‐4 expression by tumour cells was detected in 13/24 (54%, score 1–2) and 18/24 (75%, score 1) melanomas, respectively." (PMID 39789732, 2025). "In melanoma patients receiving anti-PD-1 or CTLA-4 therapy, circulating MDSC numbers initially increased in responders but subsequently declined." (PMID 40674934, 2025). "Collectively, these studies highlight a translational gap between the early promise of CTLA-4 inhibition observed in melanoma and its limited success in lung cancer." (PMID 41303538, 2025). "Significant elevations in AST and ALT levels are observed in melanoma patients receiving combination treatment based on CTLA-4 and PD-1 inhibition." (PMID 41153639, 2025). "Ipilimumab is an anti-CTLA-4 humanised monoclonal antibody (mAb) most commonly used for melanoma patients." (PMID 40361330, 2025). "It has been more than a decade since anti-PD-1 and anti-CTLA-4 antibodies were first introduced for the treatment of unresectable melanoma." (PMID 40647561, 2025). "In this study, we used a murine model of melanoma, cognitive function tests, and neuroimmunological assays to investigate the cellular mechanisms and impact of combinatorial blockade of CTLA-4 and PD-1 on brain function." (PMID 40605058, 2025). "Immune checkpoint inhibitors such as anti-PD-L1 and anti-CTLA-4 antibodies are already approved for clinical use in various cancer types, including melanoma and renal cell carcinoma." (PMID 40591551, 2025). "In our experimental setting, the efficacy of anti PD-1 mAb, permbrolizumab, and anti CTLA-4 mAb, ipilimumab, is restricted to just one melanoma cell line." (PMID 39837817, 2025). "It was found that high levels of TLSs correspond to longer OS in melanoma patients receiving anti-CTLA-4 immunotherapy." (PMID 40612858, 2025). "In melanoma, daily injections of guadecitabine, a dinucleotide prodrug of decitabine, in combination with anti-PD-1 and anti-CTLA-4 mAbs were found to reduce in vivo tumor growth." (PMID 40317004, 2025). "In patients with melanoma, combination blockade using nivolumab (anti-PD-1) and ipilimumab (anti-CTLA-4) improved the objective response rate (ORR), progression-free survival (PFS), and overall survival (OS), as compared to ipilimumab alone." (PMID 40463388, 2025). "Dr. Allison was awarded the Nobel Prize for his groundbreaking discovery of CTLA-4, and the development of ipilimumab has revolutionized melanoma treatment." (PMID 40606990, 2025). "Since the FDA approval of the CTLA-4 antibody ipilimumab in 2011 for the treatment of advanced melanoma, several antibodies targeting CTLA-4, PD-1, and PD-L1 have been approved for various cancers." (PMID 40087690, 2025). "In anti-CTLA-4 therapy in stage IV melanoma, higher levels of methylation at the CTLA-4 promoter were associated with progression, while lower levels of methylation were associated with progression-free survival." (PMID 40307913, 2025). "PD-1 and CTLA-4 are key immune checkpoint receptors that suppress T-cell activity, allowing melanoma cells to evade immune detection." (PMID 40161129, 2025). "PEBP1 and STK11 transcript levels were associated with immunosuppressive properties and responses to immune checkpoint blockade (ICB) therapies, such as anti-PD1 and anti-CTLA4, particularly in melanoma, kidney, and lung cancers." (PMID 40806276, 2025). "In subsequent years, other non-CAR approaches enhanced γδ T cell efficacy, such as inhibiting CD3ε for better tumor killing and using monoclonal antibodies against CTLA-4 and PD-1 to treat melanoma, yielding positive preclinical results." (PMID 40148988, 2025). "C57BL/6 J mice bearing RIPK3−/− melanomas showed diminished tumor control and poor survival when undergoing combined therapy with anti-PD-1 and anti-CTLA-4." (PMID 40345706, 2025).